INS (insulin)
Diseases named in the same sentence as INS in open-access papers (continued):
Sharing a sentence is not in itself a finding about the gene and the disease.
Insulin resistance (continued). "In further support of this, although obesity has been associated with insulin resistance, only 8% of individual differences in insulin sensitivity can be explained by differences in BMI." (PMID 41009753, 2025). "The primary pathological mechanisms underlying DM involve either inadequate insulin secretion or the presence of insulin resistance, resulting in sustained elevations in blood glucose levels." (PMID 40964162, 2025). "One of its hallmark features is insulin resistance, the body's failure to respond to the hormone insulin." (PMID 40673659, 2025). "SM C18:0 was associated with insulin resistance and inflammation, while SM C14:0, C22:3, and C24:4 were related to insulin secretion and glucose tolerance." (PMID 41002958, 2025). "Dysregulated miRNAs have been linked to impaired insulin secretion, insulin resistance, and chronic inflammation in type 2 diabetes." (PMID 41295241, 2025). "In the cross-sectional cohort, a higher fasting RER was associated with higher fasting glucose, insulin, and Homeostatic Model Assessment for Insulin Resistance." (PMID 40182182, 2025). "Collectively, these findings highlighted that enhanced insulin-stimulated salt reabsorption alongside impaired vasodilation play important roles in the development of hypertension associated with insulin resistance." (PMID 40725728, 2025). "Diets rich in low-GI foods are associated with improved insulin response and a lower risk of developing insulin resistance, a key factor in the development and progression of type 2 diabetes." (PMID 40026940, 2025). "Type 2 diabetes is caused by a progressive decline in β-cell insulin secretion due to various environmental and genetic factors, frequently occurring in the context of insulin resistance." (PMID 40361840, 2025). "At the same time, burnout has been associated with insulin resistance, and adults with severe burnout symptoms exhibit significantly elevated levels of both glucose and insulin in response to an oral GTT." (PMID 41441197, 2025). "A major factor contributing to this condition is the development of insulin resistance, which involves the impairment of the insulin signaling pathway and has been linked to metabolic inflammation." (PMID 39198360, 2025). "Strategies that increase NO bioavailability have potential therapeutic benefits for improving insulin sensitivity and preventing vascular complications associated with insulin resistance." (PMID 40564010, 2025). "T2DM is mainly characterized by insulin resistance, often associated with obesity, oxidative stress, and inflammation, along with impaired insulin secretion that ultimately leads to disordered glucolipid metabolism." (PMID 41181590, 2025). "Leptin and adiponectin have opposing effects: Increased leptin is associated with insulin resistance and an increase in proinflammatory cytokines, while increased adiponectin is associated with insulin sensitivity and anti-inflammatory effects." (PMID 40985048, 2025). "NP exposure that disrupts this pathway can decrease insulin sensitivity, thus increasing the risk of insulin resistance, a hallmark of Type 2 diabetes." (PMID 41030587, 2025). "Specifically, exercise would seem to increase serum adiponectin, an important regulator of insulin sensitivity, and reduce leptin, a pro-inflammatory marker associated with insulin resistance." (PMID 40431370, 2025). "It has been shown that miRNA-378 is involved in the regulation of insulin sensitivity through counteracting PGC1b and is associated with the development of insulin resistance." (PMID 40943138, 2025). "This dysregulation led to a reduction in insulin sensitivity, as evidenced by a significant increase in the activity of key enzymes associated with insulin resistance, such as DPP-4 and PTP1B." (PMID 40376699, 2025). "Insulin balance plays an important role in maintaining muscle mass and function, with both insulin resistance and insulin deficiency promoting the occurrence and progression of sarcopenia." (PMID 40507924, 2025).
Insulin resistance (continued). "We report on exploratory analyses of sex-specific associations between diet and insulin sensitivity, insulin resistance, and android and intermuscular fat composition in older adults." (PMID 41228532, 2025). "Altogether, our studies support the critical role of hepatic ChREBP in triggering insulin-sensitive signals and explore ways to target ChREBP to curb metabolic syndromes linked with insulin resistance like NAFLD and T2DM." (PMID 40311678, 2025). "For instance, elevated fasting insulin and abnormal glucose tolerance can indicate early metabolic dysfunction, whereas more severe insulin resistance and hyperglycemia are associated with advanced disease." (PMID 40427524, 2025). "The IRS1/PI3K/AKT pathway is a major signaling pathway associated with insulin resistance, mediating insulin-stimulated glucose uptake and utilization." (PMID 40565724, 2025). "Some of the male-specific overrepresented pathways in endothelial cells included insulin signaling and insulin resistance, pathways of consequence as insulin resistance associated hyperinsulinemia promotes impaired cognition." (PMID 41310161, 2025). "Specific genetic variations in genes related to lipid metabolism and insulin signaling pathways can heighten the risk of dyslipidemia and insulin resistance, thereby exacerbating metabolic disturbances." (PMID 40280905, 2025). "Insulin resistance is commonly linked to elevated insulin levels and is considered the central component of metabolic syndrome." (PMID 41164182, 2025). "Muscles also become better at absorbing glucose, enhancing insulin sensitivity, and reducing the risk of insulin resistance, particularly in those predisposed to metabolic conditions like Type 2 diabetes." (PMID 41141371, 2025). "This review underscores the importance of maintaining proper insulin levels to lower the risk of insulin resistance." (PMID 40725728, 2025). "Low Mg levels have been associated with insulin resistance and metabolic syndrome, as Mg regulates ion channels, cellular processes, and physiological functions and is involved in insulin signaling pathways." (PMID 41235310, 2025). "This SNP, implicated in insulin secretion and islet development, was also associated with systolic BP, insulin resistance and CVD in the Chinese population." (PMID 39579208, 2025). "ROS are involved in the onset of inflammation in pancreatic islets, and pancreatic cell death inevitably results in loss of insulin secretion by β-cells, which, in turn, exacerbates insulin resistance." (PMID 39968090, 2025). "Accordingly, genome-wide association studies have shown that candidate genes in T2D are rather associated with beta cell development or insulin secretion than with insulin resistance." (PMID 40531860, 2025). "EKA occurs due to relative or absolute carbohydrate deficit and insulin resistance or deficiency, leading to increased glucagon-to-insulin ratio." (PMID 39801610, 2025). "Insulin-stimulated flux through ATP synthase was associated negatively with insulin resistance and HbA1c." (PMID 39998445, 2025). "Other studies have similarly reported that TLR2-deficient mice show improved insulin sensitivity and enhanced hepatic insulin signaling and are protected from high-fat diet-induced insulin resistance and pancreatic beta cell dysfunction." (PMID 40558558, 2025). "Type 2 diabetes (T2D) is characterized by insulin resistance stemming from a general loss of insulin sensitivity in cells and tissues." (PMID 39947478, 2025). "Type I dInr genotypes are manipulations that reduce insulin signaling and extend lifespan but retard growth, slow development, repress fecundity, and cause insulin resistance." (PMID 40523036, 2025). "The reasons implicated include an increase in insulin resistance, reduction of insulin secretion and an escalation in the hepatic glucose output." (PMID 40735043, 2025).
Insulin resistance (continued). "Type 2 diabetes mellitus (T2DM) is a critical non-communicable, chronic metabolic disease, primarily characterized by the presence of insulin resistance due to the gradual loss of insulin secretion from islet β-cells." (PMID 40728998, 2025). "Previous studies have demonstrated that insulin resistance is closely associated with chronic low-grade inflammation, oxidative stress, and impaired insulin signaling pathway." (PMID 41586243, 2025). "Insulin resistance associated with obesity results in elevated insulin and insulin-like growth factor 1 (IGF-1) levels, which activate PI3K-AKT and (Mitogen-Activated Protein Kinase) MAPK signaling pathways critical for cell proliferation and survival." (PMID 41301707, 2025). "A recent meta-analysis highlighted the link between insulin resistance and thyroid carcinoma, revealing that both elevated fasting serum insulin levels and insulin resistance are associated with a higher risk of developing thyroid cancer." (PMID 40731899, 2025). "GLUT4 is required for glucose uptake in insulin-sensitive tissues, such as the AT, and its reduction is normally associated with obesity-induced insulin resistance." (PMID 40227203, 2025). "Elevated BCAAs have been causally linked to insulin resistance and are intricately associated with impaired insulin signaling pathways." (PMID 40280905, 2025). "In a subset of a large population‐based cross‐sectional analysis, higher bicarbonate levels were associated with lower fasting insulin concentration, whereas lower bicarbonate levels were associated with insulin resistance." (PMID 41378230, 2025). "Multi-organ insulin resistance and a reduction in beta cell insulin secretory function are the causes of this condition." (PMID 40407432, 2025). "KEGG enrichment analysis indicated that these genes were associated with the insulin signaling pathway and insulin resistance." (PMID 40642528, 2025). "Although progesterone is crucial for triggering the secretion of insulin in the early stages of pregnancy, as pregnancy progresses, elevated progesterone levels cause insulin resistance." (PMID 41013820, 2025). "NFIL3 overexpression in the liver promotes gluconeogenesis, disrupts lipid metabolism and insulin signalling, induces insulin resistance in the liver and muscles, and increases the risk of metabolic syndrome." (PMID 40177474, 2025). "The hallmark of obesity-induced insulin resistance (IR) is compromised insulin function, which suppresses hepatic glucose production and increases muscle and adipose tissue glucose uptake." (PMID 40283443, 2025). "Insulin has been associated with an elevated risk of lung cancer, as higher fasting serum insulin levels and insulin resistance are correlated with an increased likelihood of developing the disease." (PMID 40017690, 2025). "Activated AMPK improves metabolic status by regulating signaling pathways and metabolic pathways associated with insulin resistance to enhance insulin sensitivity to treat MAFLD." (PMID 40727101, 2025). "DM is a common endocrine disorder caused by chronic hyperglycemia resulting from insulin resistance or insufficient insulin secretion." (PMID 41255514, 2025). "Insulin resistance is a key pathogenic feature of metabolic syndrome, and NAFLD is closely associated with reduced systemic insulin sensitivity and increased insulin resistance in the liver and adipose tissue." (PMID 41050396, 2025). "Excessive lipid storage predisposes individuals to insulin resistance, as large dysfunctional adipocytes exhibit reduced insulin sensitivity and secrete pro-inflammatory cytokines (e.g., TNF-α, IL-6), further exacerbating metabolic dysregulation." (PMID 40218884, 2025). "Insulin resistance, a feature of advanced type 2 diabetes, can also be a cause of this syndrome because it renders the body less sensitive to insulin, requiring greater dosages or polypharmacy regimens to be controlled." (PMID 40786180, 2025).
Insulin resistance (continued). "This study reveals distinct phospholipid profiles linked to insulin resistance and sensitivity, with glycerophospholipids strongly associated with insulin resistance and sphingomyelins and plasmalogens correlated with insulin sensitivity." (PMID 40422918, 2025). "Adiponectin is an adipokine with anti-inflammatory and insulin-sensitizing properties, and its deficiency has been linked to the pathogenesis of insulin resistance and type 2 diabetes." (PMID 40362737, 2025). "MBV insulin resistance in CD36-deficient individuals is supported by findings in cultured hMECs where CD36 depletion impairs insulin signalling and eNOS activation." (PMID 39503770, 2025). "Both maternal GDM and obesity have been linked to increased insulin resistance and insulin secretion in offspring." (PMID 40544417, 2025). "Brain insulin resistance emerges as a pathological hallmark of AD, leading to dysregulation in metabolism, inflammation, oxidative stress, impaired insulin signalling, mitochondrial dysfunction and synaptic dysfunction." (PMID 40818936, 2025). "Consistent with our results, metabolites of DEHP have been associated with an increase in fasting glucose, insulin, and insulin resistance, and reduction in glucose control in adolescents, adults, and elderly adults." (PMID 41154898, 2025). "Higher VAT is associated with increased inflammation and insulin resistance, and increased insulin levels are in turn associated with OSA—even after adjusting for BMI." (PMID 40472801, 2025). "Critically, obesity-associated chronic inflammation disrupts insulin signaling pathways, serving as a central mechanism in the pathogenesis of insulin resistance." (PMID 40181314, 2025). "Meanwhile, these inflammatory factors can also interfere with the insulin signaling pathway, leading to insulin resistance and thereby causing a series of metabolic disorders such as elevated blood sugar and dyslipidemia, further aggravating the CMM." (PMID 41497479, 2025). "Together, these examples indicate that insulin resistance caused by a molecular defect in insulin signaling can lead to secondary hyperinsulinemia." (PMID 40013621, 2025). "Weight gain associated with insulin therapy further complicates long‐term management by exacerbating insulin resistance, creating a vicious cycle of escalating dosage requirements." (PMID 40919135, 2025). "By comparing the FLI with established markers of insulin resistance and insulin secretion, we further evaluated its ability to reflect underlying insulin sensitivity and β-cell function." (PMID 40570015, 2025). "Total lipids, triglycerides, fasting blood glucose, and insulin levels further emphasized metabolic disparities, with insulin resistance linked to higher alkaline phosphatase and lower hemoglobin levels." (PMID 40226143, 2025). "For example, hepatocytes develop metabolic alterations leading to insulin resistance (IR), whereas pancreatic beta cells increase insulin production to compensate for IR, causing cellular stress, malfunction, reduced insulin secretion and/or cellular death." (PMID 41373670, 2025). "Insulin resistance is the main underlying condition of metabolic syndrome, since insulin has beneficial effects on blood pressure, metabolism of lipids, and cholesterol-binding lipoproteins." (PMID 40868161, 2025). "Insulin resistance (IR) describes a state where target organs display reduced sensitivity to insulin, causing a decline in insulin’s capacity to promote the absorption and utilization of glucose in peripheral tissues." (PMID 41464992, 2025). "This is because low Mg concentrations are associated with an increased risk of insulin resistance and type 2 diabetes, and supplementation interventions have been shown to improve insulin sensitivity, even in individuals with normal baseline Mg levels." (PMID 41303592, 2025). "Hs-CRP and fasting insulin were significantly associated with insulin resistance (P values > 0.05 for all)." (PMID 40641901, 2025).
Insulin resistance (continued). "By binding to angiotensin II receptor type 1 receptors, angiotensin II activates downstream MAPK and JNK signaling pathways, leading to the inhibition of the insulin signaling pathway and subsequently causing insulin resistance." (PMID 40365304, 2025). "This contrasts with the findings of a study of obese Chilean subjects with positive HAdV-36 seroprevalence, which was associated with insulin resistance and low glucose and insulin levels." (PMID 40136420, 2025). "Their deficiency in animal models induces hepatic insulin resistance, while in humans, estrogen therapy has shown protective effects by reducing visceral fat accumulation and improving insulin sensitivity." (PMID 40278371, 2025). "P. gingivalis disrupts the body’s insulin signaling pathways, leading to insulin resistance and potentially increasing the risk of DM." (PMID 41296433, 2025). "Throughout her hospitalization, she required higher insulin doses than expected, raising suspicion for an underlying secondary cause of insulin resistance." (PMID 40584808, 2025). "IFN-γ causes insulin resistance in skeletal muscle and stimulates phenotypic changes in human adipocytes impaired by INS action." (PMID 40940769, 2025). "Although insulin resistance is sufficient to cause hyperglycemia, enough insulin is present to lower the levels of counter-regulatory hormones in the blood and to inhibit lipolysis." (PMID 41141170, 2025). "Metabolic acid loads have been associated with impaired glucose homeostasis and insulin resistance because metabolic acidosis interferes with intracellular insulin signaling pathways." (PMID 41437079, 2025). "Until 1982, animal-derived insulin was the only therapeutic option for T1DM, but its use was associated with the formation of anti-insulin antibodies leading to insulin resistance and lipoatrophy." (PMID 40480914, 2025). "Type 2 diabetes is caused by both insulin resistance and insufficient insulin secretion and is influenced by lifestyle factors such as overeating, physical inactivity, obesity, stress, and aging." (PMID 40650275, 2025). "High levels of plasma glutamate have been associated with metabolic dysfunction and insulin resistance due to a dysregulated glutamate/receptor axis and insulin secretion in pancreatic β-cells." (PMID 39997700, 2025). "In patients with T2DM, the increased expression of TLR2, TLR4, and plasma LPS is associated with plasma insulin concentration and insulin resistance." (PMID 40076851, 2025). "Research has demonstrated that oxidative stress causes insulin resistance by disrupting insulin signaling." (PMID 40283443, 2025). "Insulin resistance due to kinase/mTOR inhibitors or corticosteroids needs to be treated with insulin sensitizers, and insulin deficiency due to immunotherapy or post-pancreatitis/pancreatic cancer needs mandatory supplementation of insulin." (PMID 40735043, 2025). "Even though the connection between insulin resistance and obesity is multifaceted and associated with many molecular processes, high insulin levels are commonly associated with insulin resistance in children and adolescents." (PMID 40565251, 2025). "Since insulin promotes protein synthesis and inhibits proteolysis, we can predict that states of insulin deficiency or insulin resistance would be associated with hyperaminoacidemia." (PMID 40362828, 2025). "Initial insulin resistance-induced upregulation of insulin secretion by pancreatic beta-cells causes hyperinsulinemia and promotes senescence in adipocytes, endothelial cells, T-cell, and macrophages in VATs." (PMID 40696355, 2025). "T2DM is characterized by a progressive decline in pancreatic β-cell insulin secretion and increased peripheral insulin resistance, and it is strongly associated with MASLD as a major contributor to chronic liver injury." (PMID 41462693, 2025). "Concurrently, skeletal muscle loss exacerbates insulin resistance by reducing insulin-mediated glucose uptake, a key driver of atherosclerosis." (PMID 40625352, 2025).